MEGF6 (multiple EGF like domains 6)
Synonyms: EGFL3
Tractability: Antibody: UniProt places it where antibodies can reach, with high confidence; UniProt predicts a signal peptide or a membrane-spanning region; its Gene Ontology location is reachable by antibodies, with medium confidence.
Gene: Protein-coding gene on chromosome 1 (3,487,942 to 3,611,543, reverse strand). Ensembl gene ENSG00000162591.
Subcellular location: Secreted
Subcellular location (Human Protein Atlas): Microtubules; Cytokinetic bridge; Predicted to be secreted
Gene Ontology:
Molecular function: protein binding; scavenger receptor activity; calcium ion binding
Biological process: vesicle-mediated transport
Cellular component: plasma membrane; extracellular region
Genetic constraint (gnomAD): Loss-of-function variants: 184 observed, 169.82 expected, observed/expected ratio (o/e) 1.08, 90% interval 0.96 to 1.22. The synonymous counts are far from expectation, so gnomAD's model fits this gene poorly and the ratio says little. Missense variants: 2,282 observed, 1,936.6 expected, observed/expected ratio (o/e) 1.18, 90% interval 1.14 to 1.22. Synonymous variants: 1,038 observed, 818.15 expected, observed/expected ratio (o/e) 1.27, 90% interval 1.21 to 1.34.
Homologues: Orthologues: chimpanzee MEGF6 (96% identical), macaque MEGF6 (94% identical), pig MEGF6 (81% identical), dog MEGF6 (79% identical), mouse Megf6 (78% identical), rat Megf6 (77% identical), guinea pig MEGF6 (76% identical), tropical clawed frog megf6 (57% identical), zebrafish egfem1 (27% identical). Paralogues in human: MEGF11 (24% identical), MEGF10 (24% identical), GAS6 (10% identical).
Diseases named in the same sentence as MEGF6 in open-access papers:
MEGF6 is named in the same sentence as 18 diseases in open-access papers, as found by Europe PMC text mining. Sharing a sentence is not in itself a finding about the gene and the disease. The quoted sentences say what the papers report.
colorectal cancer (2 papers, 2019 to 2020). A primary or metastatic malignant neoplasm that affects the colon or rectum. "Little is known about the role of MEGF6 in any system, though it has been shown to promote the metastasis of colorectal cancer by inducing EMT." (PMID 32078629, 2020).
neuroblastoma (2 papers, 2019 to 2023). Neuroblastoma (NB) is the most common solid, extracranial childhood tumor. "Here, we also found that higher Megf6 transcript levels are associated with poor outcome in this neuroblastoma subset, and this is consistent with our RNA-seq data and the delayed tumorigenesis observed in the Th-MYCN/Casp2−/− mouse model." (PMID 30670683, 2019). "We used R2: Genomics Analysis and Visualization Platform, to examine the correlation between Megf6 transcript expression and clinical outcome in various human neuroblastoma and B-cell lymphoma publicly available expression array data sets." (PMID 30670683, 2019).
B-cell lymphomas (1 paper, 2019). "In contrast, we found there was a trend for lower Megf6 expression being predictive of poorer B-cell lymphoma outcome (e.g., Xiao – 420, fRMA-u133p2 dataset; P = 0.061)." (PMID 30670683, 2019). "The lack of clinical correlation with Megf6 expression in B-cell lymphoma may be indicative of a tissue-specific function for Megf6 and/or that Casp2 loss can cooperate with high Megf6 expression to augment lymphomagenesis in the EμMyc/Casp2−/− model." (PMID 30670683, 2019). "Notably, high Megf6 expression in B-cell lymphomas also showed a somewhat poor survival outcome, indicating that Megf6 levels are probably not predictive of lymphoma progression." (PMID 30670683, 2019).
cystinuria (1 paper, 2017). Cystinuria is a renal tubular amino acid transport disorder characterized by recurrent formation of kidneys cystine stones. "Up-regulated genes included several genes (SLC7A9, SEMG1, SBSPON and MEGF6) that were not well functionally characterized (except SLC7A9, a marker for cystinuria) and are not discussed here." (PMID 29284484, 2017).
Krebs 2 carcinoma (1 paper, 2022). "The obtained data confirmed the strong overexpression of Mreg, Prg4, Col3a1, Selp, Marco, and Fgfr1 genes in Krebs-2 carcinoma, as well as Cdh11, Col4a5, Vcam1, Megf6, Scarf2, Scart1, and Cd14 genes in HH47." (PMID 36555446, 2022).
lung adenocarcinoma (1 paper, 2021). A carcinoma that arises from the lung and is characterized by the presence of malignant glandular epithelial cells. "The heatmap reveals that HNRNPLL|53258|AT, CA5B|98313|ES, MEGF6|315|ES, and CDKN2A|86000|AP may have positive effects on lung adenocarcinoma while BEST3|23330|AT, TTC39C|44852|AP, AP2B1|40327|AD, LETM2|83399|AT, and MKL1|62348|AP can have adverse effects." (PMID 35004299, 2021).
cancer (3 papers, 2020 to 2022). A tumor composed of atypical neoplastic, often pleomorphic cells that invade other tissues. "Only 3.9% (14/356) of discordant mutations found in xenografted liver metastases affected cancer-associated genes, including a third hit to APC, which was already biallelically inactivated in Patient #1 samples, and MEGF6 mutation in Patient #2." (PMID 32532289, 2020).
tumor (2 papers, 2019). "While we identified several unique genes that were aberrantly expressed in the Casp2−/− tumors, we found that Megf6/EGFL3 was the only gene that was differentially expressed in the two tumor types." (PMID 30670683, 2019). "Consistent with a tumor progression function, we found higher expression of Megf6 in EμMyc/Casp2−/− and lower expression in Th-MYCN/Casp2−/− tumors." (PMID 30670683, 2019). "There was also a single overlapping gene; Megf6 (Multiple EGF-Like Domains 6) differentially altered in EμMyc/Casp2−/− and Th-MYCN/Casp2−/− tumors, and this was validated by quantitative PCR in additional tumor samples." (PMID 30670683, 2019).
MEGF6 also shares sentences with these, for which no sentence is quoted: acne (1 paper); chronic obstructive pulmonary disease (1); hepatocellular carcinoma (1); hyperostosis (1); lung carcinoma (1); lymphoma (1); Osteitis (1); pulmonary fibrosis (1); SAPHO syndrome (1); synovitis (1).